RHOB (ras homolog family member B)
Diseases named in the same sentence as RHOB in open-access papers (continued):
Sharing a sentence is not in itself a finding about the gene and the disease.
tumor (continued). "RhoA and RhoC have been suggested in many studies to contribute positively to tumor development, but the role of RhoB in cancer remains elusive." (PMID 29385717, 2018). "Further, HDAC inhibitors that are known to kill tumor cells, were also shown to induce RhoB expression." (PMID 29385717, 2018). "Using the MMTV-PyT mouse model interbred with rhoB null mice, the authors found an increase in the number of early tumor lesions in rhoB−/− animals, where rhoB is deleted in both the tumor and endothelial cells." (PMID 29385717, 2018). "These unique features are what contribute to the diversity and potentially opposing functions of RhoB in the tumor microenvironment." (PMID 29385717, 2018). "Studies have shown that RhoB contributes to tumor formation by stimulating proliferation, angiogenesis, invasion and migration." (PMID 29385717, 2018). "Three-dimensional growth of isolated rhoB−/− tumor cells revealed enhanced growth in acini compared to rhoB+/− cells and increased cell proliferation compared to rhoB+/+ cells." (PMID 29385717, 2018). "Here, we discuss the dualistic role that RhoB plays as both an oncogene and tumor suppressor in the context of cancer development and progression." (PMID 29385717, 2018). "Tumors stained with CD31, an endothelial cell marker, illustrated a significant decrease in the tumor vasculature of rhoB−/− mice." (PMID 29385717, 2018). "Taken together, these observations suggest exploring the function of RhoB in tumor vascularity is necessary to provide answers on its affect throughout the overall process of tumor initiation and metastasis." (PMID 29385717, 2018). "This study highlights how in tumor cells, RhoB functions as a tumor suppressor that inhibits Akt signaling, whereas in endothelial cells, RhoB harbors a tumor promoter role by sustaining endothelial AKT signaling." (PMID 29385717, 2018). "We then analyzed RHOB expression on tumor biopsies of patients receiving EGFR‐TKI as a first‐line or as second‐ to fourth‐line therapy." (PMID 28003335, 2017). "RhoB interacts with and regulates the membrane mobility of BTN3A1, and intracellular redistribution of RhoB in different tumor cells correlated with their recognition by γδ T cells." (PMID 28649364, 2017). "To this aim, we used the chemical compound camptothecin that induces apoptosis in many normal and tumor cell lines and also promotes RhoB expression and RhoB-induced apoptosis." (PMID 28212429, 2017). "While RhoA and C promote invasion and metastasis formation through regulation of actin cytoskeleton dynamics, several findings suggest that RhoB has a tumor suppressor activity through its pro-apoptotic function." (PMID 28212429, 2017). "Although no RIT1, RRAS2, or MRAS mutations were found in the TCGA BC dataset, one tumor with undetermined ER and HER2 statuses harbored a RAC1 (P69S) mutation, and one TNBC tumor harbored a RHOB (D13Y) mutation." (PMID 28636652, 2017). "Here, our findings demonstrate that a high level of RHOB protein expression in the primary tumor impairs the response rate through a mechanism involving AKT." (PMID 28003335, 2017). "The Rho family of GTPases is composed of RhoA, RhoB and RhoC and regulates the cytoskeleton, playing essential roles in cell polarity, division, proliferation, apoptosis and tumor cell metastasis." (PMID 28741985, 2017). "Considering that RhoGDI3 has tissue-specific expression, and that the regulation of GTPases by RhoG and RhoB, is involved in invasion, migration and tumor suppression, we decided to address its possible role in the progression of PDAC." (PMID 27832197, 2016). "The interesting exception is RhoB which appears to more commonly play a tumor suppressor role, and is accordingly found at reduced levels in tumor samples." (PMID 27104658, 2016). "The Rho GTPase RhoB has been proposed to be a tumor suppressor in cancer and is downregulated in various tumors including prostate." (PMID 25630770, 2015).
tumor (continued). "RHOB is well known to be modulated in response to anticancer therapies and to control tumor cell response to ionizing radiation and cytotoxic drugs." (PMID 26098773, 2015). "Production of MMP3, 9 and bFGF were specifically found to be stimulated in tumor cells when cultured with media conditioned by RhoB -/- fibroblasts but repressed when RhoB -/- fibroblasts were irradiated." (PMID 25635683, 2015). "Beside modulation of the migratory properties of cancer cells, RhoB -/- fibroblasts seemed to modulate both vascular remodeling and immune infiltration signals in tumor cells." (PMID 25635683, 2015). "Our data also highlight the importance of using RHOB tumor levels as a biomarker to predict vemurafenib patient's response and to select those that would benefit of the combination with AKT inhibitors." (PMID 26098773, 2015). "RhoB differs from the other GTPases RhoA and RhoC in that it is postulated to be a tumor suppressor because its expression is decreased in a number of tumor cell types." (PMID 25548921, 2014). "RhoB functions as tumor suppressor genes and its down-regualtion promotes cancer cell proliferation." (PMID 24597747, 2014). "As positive regulators in proliferation and malignant transformation processes, most Rho proteins are involved in promoting oncogenesis, invasion and metastasis, but accumulating evidence points to a tumor-suppressive role for RhoB." (PMID 24223801, 2013). "A variety of growth factors present in the tumor microenvironment activate Rho proteins, especially RhoB." (PMID 23339407, 2013). "RhoB has also been reported to inhibit tumor growth, cell migration and invasion, but the mechanism by which it suppresses tumor progression and invasion is still unclear." (PMID 23538840, 2013). "We found that RhoB expression in tissue was strongly correlated with ERα and PR expression and inversely correlated with tumor grade, tumor size and count of mitosis." (PMID 23339407, 2013). "This can be explained by its potential role as a tumor suppressor and RhoB levels are attenuated commonly during malignant progression." (PMID 24279335, 2013). "The RhoB level of expression was also higher in the smaller tumor size (≤ 2 cm, median 12 (2 to 12)) as compared with larger tumors (> 2 cm, median 8 (1 to 12))." (PMID 23339407, 2013). "RhoB, in contrast to its relatives RhoA and RhoC, has been shown to function as a tumor suppressor gene on the basis of investigations of genetically RhoB-deficient strains and in human cancer cells." (PMID 23339407, 2013). "Enlargement of the photographs illustrates in the tumor cells of the ERα/PR-negative patient that RhoB is present and specifically cytoplasmic, although the staining is weak." (PMID 23339407, 2013). "In contrast, RhoB was often down-regulated, low-expression of RhoB was inversely correlated with tumor aggressiveness." (PMID 22860091, 2012). "These cells also have low levels of RhoB, and re-expression of RhoB decreases proliferation and tumor growth in vivo." (PMID 21373644, 2011). "RhoB has essentially been described in tumor cells where it seems to act as a tumor suppressor gene." (PMID 21347332, 2011). "mDia-family formins act as effectors for Rho-family small GTP-binding proteins including RhoB, which has also been shown to possess tumor suppressor activity." (PMID 19768111, 2009). "It activates RhoB, which is down-regulated in multiple tumour types and is necessary for apoptosis in response to DNA damage in transformed cells." (PMID 18840272, 2008). "It has been shown that ectopic expression of RhoB in human tumor cells led to an inhibition of tumor growth in nude mice and that inactivation of RhoB in knock-out mice increased the frequency of tumors." (PMID 18047684, 2007). "As compared to the normal tissue, about 10–30% of the tumours revealed either enhanced levels of rhoB and rhoC mRNA or even reduced levels of rhoA and rac1 mRNA." (PMID 12237774, 2002).
tumor (continued). "We show that the level of RhoA, RhoB, Rac1 and Cdc42 protein is largely enhanced in all tumour samples analysed (n=15) as compared to normal tissues originating from the same individual." (PMID 12237774, 2002). "Re-expression of RhoB reduces proliferation and tumor growth in vivo." (PMID 40655948, 2025). "Many studies have shown that RhoB may have antitumor activity and can inhibit the malignant transformation of tumor cells." (PMID 40655948, 2025). "Therefore, it is likely that RhoB is a tumor suppressor that turns into an oncogene in different cellular contexts." (PMID 41301045, 2025). "Therefore, RhoB is likely a tumor suppressor that turns into an oncogene in different cellular contexts." (PMID 41301045, 2025). "However, in AR-positive tumors, it is likely that AR status plays a role in the differential effect of RhoB as a tumor suppressor vs. tumor promoter." (PMID 41301045, 2025). "In contrast to RhoA, RhoB has a more tumor-suppressive role in PCa." (PMID 41301045, 2025). "The knockdown of RhoB in HeLa and CaSki cells showed decreased tumor cell proliferation, increased apoptosis, and decreased migration and invasion, suggesting that RhoB may exert a cancer-promoting influence in CC." (PMID 39336777, 2024). "The downregulation of the RhoB in various tumor cell types has led to the hypothesis that it might function as a tumor suppressor." (PMID 38355625, 2024). "In addition, manual analysis of RhoB expression in cancer biopsy is more limited than the analysis of tumor tissues obtained from surgical resection." (PMID 36937315, 2023). "Finally, low RhoB expression in human PDAC samples, which mimics the behaviour of S100PBP described in our previous study, firmly implicates S100PBP in the same RhoB signalling circuitry and suggests its tumour suppressive functions." (PMID 37794133, 2023). "Evidence of tumor formation was found in mice when RhoB was deleted." (PMID 36937315, 2023). "In addition, RhoA and RhoC are carcinogenic and related to cell proliferation, migration, and invasion, whereas RhoB is a tumor suppressor and promotes cell apoptosis." (PMID 36320006, 2022). "As a well-known tumor suppressor, RhoB was reported to be relevant to cisplatin resistance." (PMID 35538494, 2022). "Furthermore, 4 common prognosis-associated genes (RHOB, TALDO1, HLA-DPA1, and TKT) were significantly overexpressed in the paired tumor tissue and blood." (PMID 35856557, 2022). "RhoB acts as both an oncogene and a tumor suppressor in a context-dependent manner." (PMID 34187934, 2021). "Consistent with the results of in vitro experiments, miR-30b-3p overexpression could promote tumor progression by decreasing RHOB and increasing Ki-67, CDK2, and CDK6." (PMID 33408780, 2021). "For example, several lines of evidence suggest that RHOB farnesylation may have contextual roles in tumor progression and survival." (PMID 34771475, 2021). "Taken together, these data suggested that RhoB might function as a tumor suppressor in HER2/EGFR-double positive breast cancers." (PMID 34187934, 2021). "RHOB is generally downregulated and functions as a tumor suppressor in various tumor types." (PMID 33408780, 2021). "Overexpression of RhoB inhibited tumor cell proliferation and also facilitated their apoptosis." (PMID 34093823, 2021). "Our study demonstrates the importance of PTEN and RHOB not only for primary and metastasizing tumors, but also for circulating tumor cells upon entry into a stiffer environment, where RHOB inhibitors could play an essential role for improved therapy." (PMID 34680293, 2021). "Thus, RhoA and RhoC are generally believed to act as tumor promoters, whereas the role of RhoB in human cancer is somewhat controversial." (PMID 32392742, 2020).
tumor (continued). "It was later determined that RhoB elicits this tumor suppressive function in cell lines by inhibiting basal phosphorylated Akt levels of all three isoforms (Akt1, 2 and 3) through modulation of the level of epidermal growth factor receptor (EGFR) on the cell surface." (PMID 32992837, 2020). "Furthermore, RhoB has been shown to positively correlate with proliferation, conflicting with previous studies showing a tumor suppressive function of RhoB in tumor initiation." (PMID 32992837, 2020). "As RhoB is required for apoptosis in cells transformed by DNA-damaging agents, its loss increases double-strand break (DSB) mediated genomic instability and tumor progression and promotes tumorigenesis." (PMID 31200451, 2019). "RhoB expression has also been noted to be higher in tumor vessels compared to adjacent vessels." (PMID 31174284, 2019). "In contrast, RhoB exhibited tumor suppressor functions by promoting cell apoptosis." (PMID 31097692, 2019). "One would have expected that, in the absence of p27, additional loss of RhoB would have a cumulative effect, if the tumour suppressor activities of the two proteins act on independent pathways." (PMID 30549261, 2019). "A dualistic role of RHOB was reported, it could be a proto-oncogene or a tumor suppressor depending on the context of cancer development and progression." (PMID 31540229, 2019). "RhoB plays an opposing role in tumor progression mostly acting as a tumor suppressor." (PMID 31488179, 2019). "This response may be integral in understanding RHOB’s role as a tumor suppressant and its decreased expression in aging." (PMID 31200451, 2019). "This further highlights that the function of RhoB may depend on the influence of the microenvironment, such as immune cells, and how they interact with the tumor cells." (PMID 29385717, 2018). "This investigation underscores a dual role for RhoB in tumor progression." (PMID 29385717, 2018). "Moreover, this shows that within the same tumor RhoB can have both a tumorigenic and tumor suppressive role depending on the cell type and that it is possible for one function to dominant over the other." (PMID 29385717, 2018). "However, caution should be taken to extrapolate these results to other tumor types due to the context-dependency of RhoB function as well as potential differences in the response to hypoxia." (PMID 29385717, 2018). "Although early studies indicated that RhoB had a positive role in cell growth, more recent investigations have shown that RhoB is downregulated in some tumors, suggesting that RhoB may also act as a tumor suppressor." (PMID 29385717, 2018). "In contrast, this study revealed in both tumor tissues, tumor cells isolated from rhoB−/− mice and shRhoB MDA-MB-231 cells, increased levels of activated p-AKT were detected compared with the respective controls, potentially promoting a tumor suppressing function of RhoB." (PMID 29385717, 2018). "RhoB is recognized as a tumor suppressor due to its role in regulating cell cycle and apoptosis." (PMID 30297842, 2018). "The difference in these findings has led to controversy as to whether RhoB promotes or suppresses tumor growth." (PMID 29385717, 2018). "Additionally, cells transfected with different RhoB constructs (only RhoB-F, only RhoB-GG or both RhoB-F/GG) and subcutaneously implanted into the flank of nude mice suppressed tumor growth when compared to the corresponding empty vector." (PMID 29385717, 2018). "RhoB is a tumor-inhibiting factor as indicated by many studies." (PMID 28404912, 2017). "RHOB is a RAS‐related monomeric GTPase that displays tumor suppressor activity in NSCLC." (PMID 28003335, 2017).
tumor (continued). "Indeed, the observation that the majority of patients showed an increase in RHOB tumor expression after relapse further supports a role of RHOB in EGFR‐TKI resistance." (PMID 28003335, 2017). "The results presented here demonstrate that RHOB expression is predictive of EGFR‐TKI response and suggest that an EGFR‐TKI–AKT inhibitor combination may provide a clinical advantage to prevent resistance to EGFR‐TKI in RHOB‐positive tumor patients." (PMID 28003335, 2017). "More recently, we showed that RHOB levels are not only a strong prognostic factor for NSCLC but that its downregulation is also critical for the acquisition of an aggressive phenotype of adenocarcinoma in an EGFRL858R‐induced tumor model in mice." (PMID 28003335, 2017). "In the present study, our hypothesis was that scarring signals including TGF-β and RhoB that are activated by irradiation in the stroma could enhance tumor aggressiveness after radiation therapy." (PMID 25635683, 2015). "The induction of RHOB after MAPK pathway inhibition suggests that this phenomenon could be a common feature for BRAF-mutant tumor cells." (PMID 26098773, 2015). "RhoB has been postulated to act as a tumor suppressor in cancer and regulate apoptosis." (PMID 25630770, 2015). "Interestingly, there was a significantly enhanced expression of RhoB after treated with HDACi, and meanwhile the growing tumor cells apparently decreased with obvious apoptosis." (PMID 24223801, 2013). "RhoB protein levels in normal ovaries and tumor differentiotion." (PMID 24223801, 2013). "By contrast to RhoA and RhoC reported to be up-regulated in several types of cancers, RhoB displays a property that may participate in tumor suppression." (PMID 24223801, 2013). "RhoB not only regulates endocytic trafficking, but also acts as a tumor suppressor." (PMID 23538840, 2013). "Like RhoB, high-expression of RhoT1 was negatively correlated with tumor aggressiveness." (PMID 22860091, 2012). "RhoB plays a role in number of pathways which regulate tumor cell survival and proliferation." (PMID 21373644, 2011). "Recent studies havesuggested that RhoB is involved in tumor suppression." (PMID 21079744, 2010). "Together, these studies suggest RhoB possesses tumor suppressor activity." (PMID 19768111, 2009). "Only for rhoB and rhoC, about 30% of the tumours exhibited increase in mRNA levels." (PMID 12237774, 2002). "Similarly, in skin tumors, RhoB emerged as a potent driver of tumor progression." (PMID 39336777, 2024). "Besides, comprehending the dualistic nature of RhoB in cancers necessitates elucidating the biological factors that govern its behavior through different signaling pathways not only in tumor cells but also tumor cell microenvironment." (PMID 38355625, 2024). "We hypothesized that increased hypoxia in prostate epithelial cells and tumours induces miR-21 which in turn down-regulates RHOB; thus, we explored TCGA-PRAD datasets to investigate if miR-21 and RHOB expression shows a reciprocal expression pattern in prostate tissue." (PMID 36831632, 2023). "Furthermore, inhibition of other farnesylated proteins, such as RHEB and RHOB, may help overcome resistance to standard therapies in SCCs and additional tumor types." (PMID 34771475, 2021). "We then postulated that the PAg-treatment of tumor cell lines and/or their co-culture with Vγ9Vδ2 T cells could have an impact on RHOB activity using a fluorescent reporter based on the tripartite split-GFP system which monitors the binding of activated RHOB to RBD, one of its effector domains." (PMID 32733462, 2020). "Therefore, the regulation of endocytic traffic by RHOB in the tumor cell could be decisive for the immune response and may explain the resistance of some tumor cells that nevertheless highly express RHOB." (PMID 32733462, 2020).